SNORA5A (small nucleolar RNA, H/ACA box 5A)
Synonyms: ACA5; ACA5A/B/C
Gene: Small nucleolar RNA gene on chromosome 7 (45,104,349 to 45,104,482, reverse strand). Ensembl gene ENSG00000206838.
Gene Ontology:
Biological process: RNA processing
Cellular component: nucleolus
Homologues: Orthologues: chimpanzee SNORA5A (100% identical), macaque SNORA5A (98% identical), pig SNORA5A (84% identical), mouse Gm24313 (82% identical), rat LOC120096784 (82% identical), guinea pig SNORA5A (77% identical), rabbit SNORA5A (76% identical). Paralogues in human: SNORA5B (90% identical), SNORA5C (67% identical).
Diseases named in the same sentence as SNORA5A in open-access papers:
SNORA5A is named in the same sentence as 3 diseases in open-access papers, as found by Europe PMC text mining. Sharing a sentence is not in itself a finding about the gene and the disease. The quoted sentences say what the papers report.
breast carcinoma (1 paper, 2024). "We investigated the expression of SNORA5A in breast cancer tissues and analyzed its relationship with various clinicopathological parameters." (PMID 39166607, 2024). "To further clarify the expression of SNORA5A in breast cancer, we evaluated SNORA5A expression levels in 118 breast cancer tissues and 32 normal breast tissues by ISH." (PMID 39166607, 2024). "Our study identified SNORA5A as a candidate for breast cancer suppressor and demonstrated its role in the immune microenvironment." (PMID 39166607, 2024). "We found that SNORA5A regulated the polarization of M1 and M2 macrophages through TRAF3IP3 in breast cancer." (PMID 39166607, 2024). "Our hypothesis was that SNORA5A interacts with TRAF3IP3 and regulates its nuclear localization signal and nuclear export signal to exert its vital role in breast cancer immunity." (PMID 39166607, 2024).
tumor (1 paper, 2024). "High expression of SNORA5A induced a high concentration of tumor-associated macrophages M1 and a low concentration of tumor-associated macrophages M2." (PMID 39166607, 2024). "We proposed that the expression of SNORA5A may affect the tumor microenvironment through TRAF3IP3, and TRAF3IP3 was chosen for further study." (PMID 39166607, 2024).
SNORA5A also shares sentences with these, for which no sentence is quoted: infarction (1 paper).